CTLA4 (cytotoxic T-lymphocyte associated protein 4)
Diseases named in the same sentence as CTLA4 in open-access papers (continued):
Sharing a sentence is not in itself a finding about the gene and the disease.
tumor (continued). "While RT+L19–IL2 resulted in superior tumor response as compared with RT alone in both CT26 and C51 tumor models, which is in agreement with our previously published data, the therapeutic outcomes of RT+anti-CTLA-4 and RT+anti-PD-L1 as compared with RT were significantly better only in CT26 tumors." (PMID 33688020, 2021). "Indeed, it has been shown that anti-CTLA4 therapy drove polyclonal expansion of TCR clones in tumor microenvironment even those not specific for tumor antigens." (PMID 34899700, 2021). "Contrary to current perceptions, studies of CTLA-4 in tumor cell biopsies and cell lines have revealed that CTLA-4 and sCTLA-4 may also be actively produced by cancer cells perhaps as a means of tumor cell mediated immune evasion." (PMID 35069536, 2021). "Activation of SRC family kinases may lead to elevated abundance of myeloid-derived suppressor cell, lack of anti-tumour immune responses and anti-CTLA4 immunotherapy resistance." (PMID 33830879, 2021). "Anti-CTLA-4 antibodies may also function by directly binding to and depleting Treg via macrophage dependent antibody-dependent cell-mediated cytotoxicity (ADCC) within the tumor microenvironment." (PMID 35069536, 2021). "Reduced CTLA4 expression on tumor-infiltrating T cells might permit increased expression of CD80/CD86 on Hodgkin-Reed-Sternberg cells, thereby increasing T cell proliferation and modifying the tumor environment." (PMID 33876323, 2021). "Engineered NDV vectors expressing apoptin, immune checkpoint blockades like anti-CTLA-4, anti-PD-1, anti-PDL, and cytokines like IL-2 and influenza virus NS1 trigger oncolytic cell death in tumor cell lines from lung and liver, tumor-bearing mice, and apoptosis-resistant cells, respectively." (PMID 34063663, 2021). "Tregs express immunoregulatory molecules (PDL1 and CTLA4) and produce immunosuppressive cytokines (IL-10, IL-35, TGF-β), which inhibit the synthesis of TNF-α, IFN-γ and IL-17 in Th1 and Th17 cells and reduce the production of perforin and granzymes in CTLs, alleviating their anti-tumor properties." (PMID 34830312, 2021). "Moreover, we found that the prominent lymphocytes infiltration was accompanied by the dominance of M2-type macrophage as well as abundant negative regulators (e.g., CTLA-4 and IDO1), which constituted a microenvironment preferentially toward pro-tumor activities and fostered tumor progression." (PMID 33796538, 2021). "Furthermore, these breast TNBC GEM models (MMTV‐PyVT, MMTV‐neu) express significantly low PD‐L1 on tumor cells and do not respond effectively to PD‐1/PD‐L1 and anti‐CTLA4 immune checkpoint therapies unless given in combination of adjuvants such as cisplatin." (PMID 33587338, 2021). "However, checkpoint inhibitors and anti-tumor immunity are not restricted to just the three candidates (CTLA-4, PD-1, PD-L1) currently described in the previous sections." (PMID 33952230, 2021). "Importantly, in these studies, no anti-tumor effect was detected when the anti-CTLA-4 antibody was used as a sole treatment." (PMID 34208396, 2021). "Furthermore, theefficacy of blocking CTLA-4, a major negative regulator of T cell activation,depends on Bacteroides species and tumours inaxenic or antibiotic-treated mice do not respond to CTLA-4 blockade." (PMID 33465324, 2021). "The action of CTLA-4 is in the lymph node, rather than in the tumor." (PMID 33794967, 2021). "The TME was assessed via flow cytometric and qRT-PCR to examine the anti-tumor immune response that we hypothesized to be responsible for the observed tumor regression, improved survival rates, and reduced metastases with these combinations of local therapy and BEMPEG plus anti-CTLA-4." (PMID 33937052, 2021). "In line with this concept, we showed that ICs are sequentially acquired by tumor–specific CD8 T cells at the tumor site, leading to a terminally exhausted population characterized by TIM-3 expression, the latter being acquired at late stages after PD-1, TIGIT, and CTLA-4 expression acquisition." (PMID 33332284, 2021).
tumor (continued). "Time-restricted feeding differentially impacted tumor growth with older, HFD-fed mice experiencing reduced renal tumor bioluminescence; however, time-restricted feeding did not alter tumor weights or intratumoral immune responses and failed to improve anti-CTLA-4 monotherapy." (PMID 34064933, 2021). "Therefore, YTN16 tumor-bearing mice were treated with ICI using anti-PD-1, anti-PD-L1 or anti-CTLA-4 mAbs, to test whether T cell-mediated immunity against YTN16 tumors could be generated." (PMID 35008270, 2021). "However, FoxP3 and CTLA-4 in tumor stroma appeared to have no prognostic effect within the study population." (PMID 34095135, 2021). "Furthermore, antibodies against surface molecules (including CD25, CCR4, CTLA-4, OX40, and GITR) exhaust Tregs in various tumor models, and molecules (such as cyclophosphamide and Raf-kinase inhibitor sorafenib) can also preferentially deplete Tregs upon systemic administration." (PMID 34138315, 2021). "TLR agonists with anti-tumor efficacy could stimulate DCs, promote Th1-type immune responses, and activate tumor specific T cells However, this CTL’s efficacy might be inhibited by PD-1/PD-L1 and CTLA-4 blockade." (PMID 34575449, 2021). "Although there are no pediatric tumor clinical trial results reported, PD-1/PD-L1 and CTLA-4 blockade might be complementary to the mechanism." (PMID 34583971, 2021). "CTLA-4 will bind to CD 80 or CD 86 receptor (also known as B7) on antigen presenting cells (APCs) with higher affinity than the CD28 receptor on CD4+ and CD8+ T cells, which will suppress costimulatory signals and inhibit activation of the helper and cytotoxic T cell response against the tumor." (PMID 33670942, 2021). "On the other hand, in cases of low-tumor burden or in fragile patients due to age, comorbidities or an ECOG PS 2, it may be more prudent to use single anti-PD-1 agents, given their better safety profile compared to the anti-PD1/anti-CTLA4 combination." (PMID 34541365, 2021). "In our study, only one patient with a B2M-mutant tumor and several metastases not restricted to peritoneal or lymphatic sites was treated with a combination of anti-CTLA-4 and anti-PD-l antibodies (ipilimumab and nivolumab) and demonstrated SD as best response." (PMID 34168989, 2021). "The percentage of PD-1-expressing CD8 + tumor-infiltrating cytotoxic lymphocytes also decreased from 22,03 ± 2,66% in Nav1.8-Cre−/hM3Dq+ to 12.99 ± 3.85% in Nav1.8-Cre+/hM3Dq+ animals, while the expression of CTLA-4 did not vary in these cells." (PMID 34784974, 2021). "PD-L1 was overexpressed in tumor cells, and CTLA-4 was activated in TILs but not tumor cells." (PMID 34526987, 2021). "TCRSeq in the same model shows that the combination of radiation and anti-CTLA4 increases the clonality of T cells in the tumor, and the proportion of antigen-specific T cells in the tumor, but no change in the distribution of TCR clones within the antigen specific population." (PMID 33968757, 2021). "Hence, curcumin has been shown to modulate the expression of CTLA4 and PDL1 and application of curcumin together with immune checkpoint blockers may establish a better approach to eradicate tumor cells." (PMID 34485117, 2021). "As a co-inhibitory receptor, CTLA-4 on Tregs inhibits co-stimulatory signaling through higher affinity binding to CD80/86 on APC compared with the co-stimulatory receptor CD28 on T cells, resulting in the impairment of the antitumor immune response and acceleration of immune evasion of tumor cells." (PMID 34899747, 2021). "Thus, combination of DDRi with ICB, such as anti-PD-1/PD-L1 or anti-CTLA-4 ICB, may initiate antitumor immunity, mediating durable tumor regression." (PMID 34930377, 2021). "When TAS and tumor epithelial cohorts were compared for the top 2500 statistically significant genes, immune responses were downregulated in BA vs WA TAS, while T cell-exhaustion pathways and the immune checkpoint gene CTLA4 were upregulated in BA vs WA tumors." (PMID 34316327, 2021).
tumor (continued). "We found that tumor purity was only negatively related to three immune genes, namely, CD8A (R = −0.18, p = 1.06 e-06), CXCR2 (R = −0.18, p = 2.90 e-07), and TNFRSF14 (R = −0.21, p = 2.58 e-09), but not to other immune-related genes, including the well-known PD1, PD-L1, and CTLA4." (PMID 34925437, 2021). "Moreover, expression of the immune inhibitory checkpoint receptor CTLA-4 (CD152) was significantly increased in tumor compared to normal epithelium (Log2 fold-change = 0.7106, P-value = 0.013)." (PMID 33142242, 2020). "Indeed, Treg depletion and Fc receptor-dependent tumor rejection have been recently reported to play a major role for Ipilimumab and other anti-CTLA-4 antibodies with respect to checkpoint blockade dependent on B7-CTLA-4 interactions." (PMID 32781690, 2020). "Administration of blocking (CTLA4, PD-1) or agonist (OX40) antibodies against these checkpoint regulators improves anti-tumor immune responses in animal models, and CTLA-4 and PD-1 antibodies have become approved immunotherapies for multiple tumor types in humans." (PMID 32075963, 2020). "Similarly, an increase of antigen-specific CD8 T cells that express PD-1, but not Tim-3, has been found in the tumor microenvironment after PD-1/CTLA-4 checkpoint blockade therapy." (PMID 32117218, 2020). "Recent findings also suggest that many of the anti-CTLA-4 antibodies with the anti-tumor activity, including ipilimumab (a fully human anti-human CTLA-4 monoclonal antibody of the IgG1 subclass), might not be acting simply as the checkpoint blocker." (PMID 32492969, 2020). "Enhanced numbers of GzmB producing CD4+ and CD8+ T cells in tumor patients after combination treatment with antibodies against PD-1 and CTLA-4 have previously been described, but this study did not perform a detailed characterization of the GzmB producing cells." (PMID 32226027, 2020). "However, when looking at the expression level, we observed relatively high expression of LAG3 and HAVCR2 in both primary and recurrent tumor and a trend of greater expression for TIGIT, CTLA4, BTLA, and PDCD1 in recurrent tumor tissue, compared to primary tumor tissue (NS)." (PMID 33352957, 2020). "Interestingly, the expression of DCK was associated with the gene markers like CCR8, STAT5b, and TGFB1 of Tregs, and PD–1, CTLA–4, LAG3, TIM–3, and GZMB of exhausted T cells after adjusting tumor purity, revealing that increased expression of DCK was associated with immunosuppression in HCC." (PMID 32690026, 2020). "Through blockade of cytotoxic T-lymphocyte antigen 4 (CTLA-4) and programmed cell death protein 1 (PD-1), negative feedback mechanisms of the immune system are inhibited, potentially resulting in very durable anti-tumor responses." (PMID 33643899, 2020). "Despite the precise function of CTLA-4 expressed on non-immune cells is largely unknown, some conflicting evidences indicate that it can affect tumor cell survival, by sustaining the proliferation or inducing apoptosis." (PMID 32781690, 2020). "Together, these studies demonstrated in two different tumor models that IL2-expanded autologous PBMC could recognize and kill tumor cells in vivo and the effect was enhanced by dual PD-1/CTLA4 blockade, but that tumor control was not durable." (PMID 33177175, 2020). "In butyrate groups, although CTLA-4 blockade could exert some anti-tumor effect, no significant reduction of the tumor growth was observed at day 20 (D20) compared to control group." (PMID 32358520, 2020). "Moreover, the expression of PD-L1 can be upregulated by IFN-γ, and the absence of IFN-γ signaling pathway in tumor cells leads to the resistance to CTLA-4 targeting therapy, so that IFN-γ is a novel biomarker to predict the response to ICIs." (PMID 33072607, 2020). "Moreover, prophylactic TNF blockade does not hinder, but rather enhances, the anti-tumor effect of anti-CTLA-4 and anti-PD-1 combination treatment." (PMID 31974523, 2020).
tumor (continued). "Interestingly, the increase in TIL growth was more profound when using tumor fragments from patients not pre-treated with anti-CTLA-4 antibody before TIL therapy compared to those pre-treated (Trial Number NCT02482090 and NCT03287674)." (PMID 32127601, 2020). "However, concomitantly with the generation of anti-tumor activated CD8+ T cells, DNA damage also upregulates some immunosuppressive mechanisms within TME, such as the expression of the immune checkpoints PD-1, CTLA-4, Tim-3 and LAG-3 on TILs." (PMID 32580514, 2020). "The early observation that CTLA‐4 blockade could enhance tumor Ag‐specific CD4+ T cell priming but could not overcome the eventual tolerization of these cells highlighted the contribution of alternative pathways to the regulation of T lymphocyte function." (PMID 32508018, 2020). "We also found that CTLA4 and IDO1, two well‐known immune checkpoints, were significantly higher in both tumor tissues and NATs than in healthy tissues, while the expression levels of VEGFB and LAG3 increased progressively in healthy tissues, NATs and tumor tissues." (PMID 33033616, 2020). "In our humanized mouse NPC-PDX model, the tumor-infiltrating CD8+ T cells expressed higher levels of PD-1 and CTLA-4, as well as LAG3, and these exhausted phenotypes might hinder the anti-tumor efficacy of ICB by suppressing their cytotoxicity and cytokine-producing capability." (PMID 32331230, 2020). "This may suggest that elevated expression of PD-1, TIM-3, CTLA-4, TIGIT, TOX, TOX2, and SIRT1 genes in the TME of CRC is induced by tumor-associated, factors, unlike VISTA, and LAG-3." (PMID 32393998, 2020). "In addition, the anti-tumor activity was completely abolished in the anti-CTLA-4 antibodies without the FcγR-binding capability." (PMID 32492969, 2020). "The OS T-reg cells expressed the canonical gene signature including the FOXP3 and IL2RA, and they also showed relatively high immune-inhibitory molecules including the CTLA4 and TIGIT, which may contribute to T-reg cell-mediated suppression of anti‐tumor immune responses in OS lesions." (PMID 33303760, 2020). "A subject of debate, however, is whether the anti-CTLA-4 antibodies act in favor of anti-tumor immune responses or not, in terms of targeting the CTLA-4 molecules expressed on regulatory T-cells (Tregs)." (PMID 32656079, 2020). "Indeed, treatment induced a specific decrease in the number of activated Tregs (CD4+/Foxp3+/CTLA4+) in the tumor microenvironment, without modulating Ki67 and HLA-DR activation markers." (PMID 32681091, 2020). "In murine glioma models, blockade of CTLA-4 could induce tumor regression and promote long-term survival without eliciting experimental allergic encephalomyelitis." (PMID 33767690, 2020). "Despite the favorable results, a preclinical study combining magnetic iron oxide nanoparticle hyperthermia and anti-PD-1 and anti-CTLA-4 with a 4T1-luc cell mouse model also showed decreased tumor volume but increased metastatic dissemination and no improvement in overall survival." (PMID 33240283, 2020). "In addition, such an IL-2 analog could be expected to synergize with anti-CTLA-4 and anti-PD-1 CPI therapy and/or vaccination through numerical expansion and further activation of tumor-specific Teff subsets." (PMID 32005826, 2020). "Interestingly, the combination of D16F7 mAb with an anti-CTLA-4 mAb (UC10-4F10-1 clone), or with an anti-PD-1 (RMP1-14 clone) (four doses of 10 mg/kg every two days) was more effective in suppressing tumor growth compared to each mAb administered as monotherapy." (PMID 33212945, 2020). "Finally, using tumor fragments from these same mice, we analyzed the production of cytokines and chemokines in the microenvironment of tumors from the flank and brain of untreated and ISV + α-CTLA-4 treated mice." (PMID 32690669, 2020).
tumor (continued). "In RANK+/+ tumors early treatment (72 h after tumor implantation) with anti-RL did not affect tumor growth; however, anti-CTLA4 combined with anti-RL reduced tumor growth to a greater extent than did single anti-CTLA4 treatment (28.5% of implanted tumors did not even grow)." (PMID 33303745, 2020). "It is unknown whether they express immune checkpoint inhibitory surface molecules (e.g., PD1, CTLA4, TIM3, LAG3, TIGIT, VISTA, or B7/H3), co-stimulatory molecules (e.g., CD80, CD86, OX40, ICOS, GITR, 4-1BB, or CD40), or other molecules found in the tumor microenvironment, such as IDO or TLR." (PMID 32756356, 2020). "Thus, we used the Tumor Immune Dysfunction and Exclusion (TIDE) algorithm and subclass mapping to estimate the clinical response of the subtypes to immune checkpoint blockade (CTLA-4 and PD-1)." (PMID 32346613, 2020). "In addition, Tcyt cells in tumour tissue expressed the activation marker natural killer group 2D (NKG2D) less often, while Th cells in tumour tissue were positive more often for the inhibitor CTLA-4." (PMID 33228141, 2020). "However, the arbitrary cutoff value (median [64Cu]NOTA-CD8a tumor-to-heart ratio of XRT + anti-CTLA-4-treated mice) used for stratification was not an indicator of overall survival." (PMID 32086762, 2020). "Tumor cells mediate immunosuppression by hijacking inhibitory checkpoint proteins such as programmed death 1 (PD-1), T cell immunoglobulin and mucin domain 3 (TIM-3), lymphocyte activation gene 3 (LAG-3), and cytotoxic T lymphocyte antigen 4 (CTLA-4) expressed at the surface of T lymphocytes." (PMID 32316916, 2020). "Hence, genetic polymorphism may impair function of molecules important for effective activity of anti-tumor response, such as CTLA-4; the SNPs of CTLA-4 and other immune checkpoints molecules have been studied in the context of variety types of cancers." (PMID 33519815, 2020). "Indeed both PD-1 and CTLA-4 are required for peripheral CD8+ T cell tolerance, so disrupting these pathways during checkpoint blockade should globally impair peripheral tolerance against both non-tumor and tumor-derived antigens." (PMID 33072137, 2020). "Notably, comparisons between free OVA-anti-CTLA4 and (OVAinMOF)@(anit-CTLA4inMOF), or between free OVA and OVAinMOF show that only MOF has no significant improvement in progression-free survival, overall survival or tumour volume." (PMID 32737343, 2020). "In the MCA101OVA model where antigen-specific T cell responses could be monitored, no modification of CTLA-4 expression levels within T cells was observed in tumor-draining lymph nodes (tDLN) in any groups." (PMID 32358520, 2020). "This could suggest that T cells expressing CTLA-4 and TIGIT accumulate in the circulation of CRC patients during the onset of disease, until they are recruited to the TME as disease progresses, resulting in their accumulation within the tumor tissue." (PMID 32393998, 2020). "Indeed, while anti-PD-1 mainly induced the expansion of specific tumor-infiltrating exhausted-like CD8+ T cell subsets, anti-CTLA-4 led to the expansion of an ICOS+ Th1-like CD4+ effector subsets other than engaging specific subsets of exhausted-like CD8 T cells." (PMID 32265933, 2020). "Tumor growth is suppressed in a xenograft Nur77/Nurr1-double knockout mouse model and the expression of Treg-signature genes, including Foxp3 and CTLA-4, is attenuated, without development of autoimmunity, but Nur77- or Nurr1-single knockout mice are not able to delay or inhibit tumor growth." (PMID 33086676, 2020). "Interestingly, IHC demonstrates increased myeloid cells and monocytes/macrophages in brain metastases after treatment with ISV + α-CTLA-4 compared with untreated mice, with no change in these cells at extracranial LF tumor with or without treatment." (PMID 32690669, 2020).